TNF (tumor necrosis factor)
Diseases named in the same sentence as TNF in open-access papers (continued):
Sharing a sentence is not in itself a finding about the gene and the disease.
schizophrenia (continued). "Other cytokines including IL1, TNF, and IFN are also disturbed in schizophrenia." (PMID 32256401, 2020). "Finally, in patients with schizophrenia, the Th1/Th2 ratio (defined as [IFN-γ]/[IL-4]) showed a significant positive correlation with admission levels of plasma IL-6 and plasma TNF-α." (PMID 32061259, 2020). "In conclusion, we found that the -1031C>T and -308G>A in the TNF-alpha gene did not appear to modify the propensity to develop schizophrenia and suicidal behaviors, but they did influence the age of suicide initiation in patients with SCZ." (PMID 31954374, 2020). "Schizophrenia (SZ) is a neurodevelopmental genetic disorder in which maternal immune activation (MIA) and increased tumor necrosis factor-α (TNF-α) may contribute." (PMID 33005129, 2020). "In another study of schizophrenia, consumption of Bifidobacterium breve A-1 for 4 weeks improved PANSS and anxiety/depression scores, increased levels of IFN-γ, IL-1R1, IL-10, IL-22, and decreased levels of TNF-α." (PMID 32226399, 2020). "Although amphetamine models do not represent heterogeneous schizophrenia disorders, based on underling mechanisms of systemic hUC-MSC, we expect stem cell therapy to be effective particularly for patients with elevated TNF-α levels in periphery." (PMID 32341334, 2020). "The IL1B/Il1b, IL6/Il6, or TNF/Tnf was not significantly upregulated in the schizophrenia postmortem brain sample and in the poly‐I:C model mice." (PMID 31657521, 2019). "Serum TNFα level does not change as long as symptoms of schizophrenia are present indicating long periods of immune stimulation." (PMID 30627222, 2018). "Taken all together, these findings suggest that the increased TNF-α and IL-1β, which may be caused by the activated microglia are related with negative symptoms of schizophrenia and anti-inflammatory may have therapeutic effects on clinical symptoms, especially on negative symptoms in schizophrenia." (PMID 29867314, 2018). "We found significantly increased TNF-α and IL-1β levels in an immune-related animal model that imitated negative symptoms in schizophrenia in our recent study." (PMID 29867314, 2018). "In one sample, human IL-8 (and not IL-6, TNF-α, or IL-1β) was elevated in the serum of pregnant women whose offspring went on to develop schizophrenia and correlated with brain changes in the offspring." (PMID 30225350, 2018). "In brain, we and others find an upregulation of IL-6 and IL-8 mRNA expression in the dorsal lateral prefrontal cortex (DLPFC) of people with schizophrenia compared to controls, but no change in TNFα." (PMID 28923068, 2017). "Pro-inflammatory cytokines such as tumor necrosis factor-α (TNF-α), IL-6, IL-1β, and interferon-γ (IFN-γ), formed by persistently actuated macrophages and T lymphocytes have also been conveyed as immunological altered components in schizophrenia." (PMID 27047333, 2016). "The crosstalk of PID candidate pathway for schizophrenia between hedgehog signaling pathway and other cancer-related pathways such as LKB1 signaling events, Aurora signaling pathway, ErbB2/ErbB3 signaling pathway and TNF alpha/NFkB signaling pathway." (PMID 25522158, 2014). "We have previously found increased TNF-α mRNA levels in the midbrain of individuals with schizophrenia that were not reflected at the protein level, suggesting increased proteolysis of TNF-α or altered expression of transmembrane/soluble TNF-α due to inflammation." (PMID 41567988, 2026). "Conversely, cytokines including TNF-α and IFN-γ, which do not normalize with antipsychotic therapy, may serve as trait markers, indicating a predisposition to schizophrenia irrespective of current disease state." (PMID 40724876, 2025). "Path-analysis was used to evaluate direct and indirect relationships between Childhood Trauma Questionnaire (CTQ) scores, serum concentrations of C-reactive protein (CRP), interleukin (IL)-6 and tumour necrosis factor (TNF)-α, and Positive And Negative Syndrome Scale of Schizophrenia (PANSS) scales." (PMID 41049865, 2025).
schizophrenia (continued). "Elevations of IL-1β, IL-6, IL-8, IL-4, and TNF-α may also exacerbate negative symptoms of schizophrenia, whereas IL-6, together with IL-13 and IL-17, may intensify general symptoms in chronic schizophrenia." (PMID 40364201, 2025). "Studies have shown that patients with schizophrenia exhibitelevated levels of monocytes, neutrophils, and C-reactive protein (CRP).Additionally, various cytokines (e.g., monocyte chemoattractant protein-1,IL-1β, IL-5, IL-6, IL-9 and TNF-α) have been reported to beupregulated in schizophrenia." (PMID 40926813, 2025). "Since both the immunological background of drug resistance in patients with schizophrenia and the effects of ECT on cytokines have been insufficiently studied, we decided to examine immunology molecules such as IL-1β, IP-10, IL-17, IL-10, TNF-α, and sIL-2 receptor in TRS patients treated with ECT." (PMID 40364201, 2025). "In particular, deficit schizophrenia, a subtype marked by primary and persistent negative symptoms, has been more strongly correlated with increased levels of pro-inflammatory mediators including IL-6 and TNF- α compared to non-deficit forms." (PMID 40806558, 2025). "Therefore, exploring the interaction of TNF-α and MMP-2 in patients with TRS and chronic medicated schizophrenia (CMS) could provide insight into the mechanisms driving treatment resistance and chronicity." (PMID 38429778, 2024). "In contrast, in patients with schizophrenia who were treated for the first time, acutely exacerbated, displayed acutely relapsed states, and who were medicated in the acute phase, TNF-α did not correlate with PANSS scores." (PMID 38429778, 2024). "In fact, according to the literature, increased TNF-α/IL-4 and IFN-γ/IL-4 ratios were verified in BP patients during manic episodes as compared with normal controls, and a relative predominance of the Th2 immune profile was evidenced in patients with acute exacerbation of schizophrenia." (PMID 38644495, 2024). "Most studies describe an increase in TNF-α in the blood in schizophrenia or no changes." (PMID 37239308, 2023). "TNF microsatellites d3 and b4 were associated with increased susceptibility to CIA, while microsatellite b5 showed a protective effect in both Jewish and non-Jewish individuals with schizophrenia." (PMID 35710824, 2022). "Nevertheless, there is no data on whether the IL-6, IL-23, and Th17 (IL-17, TNF-α, IL-21 and IL-22) axis is more associated with MNP than with SNP and whether changes in this axis are associated with the G-CoDe and the phenome of schizophrenia." (PMID 36256663, 2022). "No significant sex differences were found in the TNF-α levels of patients with schizophrenia." (PMID 34763685, 2021). "This study suggests that elevated peripheral levels of TGF-β, but not IL-6, IL-1β, TNF-α, IFN-γ or IL-10, may not only predispose one to the development of schizophrenia, but may also be a consequence of childhood trauma." (PMID 34501305, 2021). "We observed that the TNF-α levels in FEDN patients were significantly higher than those in healthy controls and chronic patients, indicating that first-episode patients with schizophrenia may have higher levels of inflammation than healthy controls, consistent with the findings of previous studies." (PMID 34763685, 2021). "A study in patients with the deficit syndrome of schizophrenia—a subgroup of patients with primary negative symptoms from the illness debut—found significantly elevated IL-6 and TNF-α in patients with deficit syndrome compared to in non-deficit schizophrenia and healthy controls." (PMID 30766494, 2018). "In a study, the diagnosis of schizophrenia was accompanied by a specific cytokine-chemokine profile, i.e., increased levels of CCL11, CCL3, soluble TNF receptors 1 and 2 (sTNF-R1 and sTNF-R2), and decreased levels CXCL10 (also known as IFN-Υ-inducible protein 10 or IP-10), TNF-α, IL-2, and IL-4." (PMID 28870209, 2017).
schizophrenia (continued). "As it has been suggested that schizophrenia may be the consequence of a vascular-inflammation, we studied the mRNA levels of SERPINA3, IFITM2, IFITM3, and GBP1 in a human endothelial cell line (TIME), before and after stimulation with TNF-α." (PMID 17822540, 2007). "We also found that a TNF-α concentration increase post-ECT could be coupled with the attenuation of negative symptoms of schizophrenia, whereas a decrease in PANSS total score (clinical improvement in schizophrenia) may be linked with an increase in sIL-2R concentration." (PMID 40364201, 2025). "Some studies reported that increased tumor necrosis factor alpha (TNF-α) levels were correlated with the psychopathology in first-episode drug-naïve patients, which suggested that inflammatory cytokines might play a crucial role in the etiopathogenesis of schizophrenia." (PMID 38956509, 2024). "If schizophrenia patients are not developing the normal immune tolerance they should be in response to stress, a period of long-term stress could result in a prolonged release of pro-inflammatory cytokines such as TNF-α." (PMID 35844244, 2022). "Thus, it is possible that TNF-α, but not IL-6 more potently activates indoleamine 2,3-dioxygenase and tryptophan 2,3-dioxygenas, two major rate-limiting enzymes of Kyn formation in the schizophrenia group than in the healthy control group." (PMID 34393855, 2021). "Increased TNF-α levels in FEDN patients and their correlation with psychopathology indicate that inflammatory cytokines may play a crucial role in the etiopathogenesis of schizophrenia, and inflammation-directed therapy may, therefore, improve negative symptoms." (PMID 34763685, 2021). "TNF-α and IL-1β were participated in the processes of neurogenesis or white matter abnormalities, suggesting that altered TNF-α and IL-1β may be associated with negative symptoms of schizophrenia." (PMID 29867314, 2018). "Our finding of reduced prevalence of atopy in schizophrenia may therefore be reflective of a shift from a TH2 to a TH1 response, though this idea is speculative since we did not measure and compare markers of TH1 response (e.g. INF-γ, TNF-α, IL-12) between schizophrenia patients and controls." (PMID 25346942, 2014). "For example, TNF-α was found to be positively correlated with PANSS negative scores in 47 antipsychotic-responders and 47 antipsychotic non-responders with schizophrenia." (PMID 38429778, 2024). "In a later lifestyle modification study in obese, non-diabetic individuals with schizophrenia, Kuo and co-workers were not able to detect significant decrease of either CRP, TNF or IL-6 after 10 weeks of intervention." (PMID 37265560, 2023). "Results in the present study reflect this evidence, since IL-6 exerts a downstream effect on TNF-α and IFN-γ, therefore playing an influential role in a non-resolving pro-inflammatory state in schizophrenia." (PMID 37723153, 2023). "Levels of interleukin (IL)-6, IL-1β, IL-12, tumor necrosis factor (TNF)-α, and transforming growth factor (TGF)-β were elevated in schizophrenia, while levels of IL-2, IL- 4, and IL-17 did not change." (PMID 35546942, 2022). "We did not detect a change in either ABCB1 or ABCC1 expression in people with schizophrenia nor in the context of high inflammation, which is in keeping with the fact that ABCB1 expression is only slightly reduced by IL-6 and increased by TNFα." (PMID 30214039, 2020). "Secondly, both TNF-α and IL-1β showed moderately positive correlations with the PANSS negative subscore in the CP but not in FEDN patients with schizophrenia." (PMID 29867314, 2018). "But until now, no study has simultaneously reported TNF-α and IL-1β in both first-episode drug-naïve (FEDN) and chronic patients (CP) with schizophrenia." (PMID 29867314, 2018). "The negative correlation between TNF-α and PANSS general psychopathology scores further complicates the inflammatory hypothesis of schizophrenia." (PMID 40791199, 2025).
schizophrenia (continued). "After treatment, IL-6 decreased both in schizophrenia and MDD, while TNF-α did not change." (PMID 30766494, 2018).
anemia (283 papers, 2006 to 2026). A reduction in the number of red blood cells, the amount of hemoglobin, and/or the volume of packed red blood cells. "Abnormally high levels of TNF and IL-10 have also been associated with P. falciparum malaria anaemia due to their suppressive effect on the bone marrow." (PMID 40406565, 2025). "In the present study, inverse significant correlations are noticed between CD4 with MDA, TNF- α and sTfR/log ferritin denoting that oxidative stress, inflammation and anemia in PD are associated with reduced CD4." (PMID 40615531, 2025). "Cancer-associated anemia is thought to be partially mediated via an increase in inflammatory cytokines, like interleukin 6 or tumor necrosis factor alpha, that are believed to negatively interfere with iron metabolism." (PMID 40867262, 2025). "For example, an Italian survey found anemia prevalence of 15% among AS using biologics, and after excluding anemia caused by other reasons, symptoms disappeared in 82% of patients after TNF-α treatment, a viewpoint corroborated by other studies." (PMID 39908327, 2025). "The development of preoperative anemia in CRC is intricately linked to inflammatory mediators such as TNF-α, IFN-γ, and various interleukins." (PMID 39649896, 2024). "Various studies showed that the inflammatory cytokines IL-6 and TNF-α played crucial roles in the development of cancer-associated anemia and cachexia." (PMID 39372868, 2024). "The higher inflammatory response in piglets without additional iron in the diet in this study is consistent with previous studies in which low iron status led to increased pro-inflammatory cytokines (including IL-1β, IL-6, and TNF-α) in iron deficiency anemia." (PMID 39296492, 2024). "The results of the ROC analysis of HPC, as was the case in cytokines IL-1β and TNFα, ranged between 0.6 and 1.0, indicating a potential diagnostic value for clinical prognosis for patients with age-associated anemia." (PMID 37240288, 2023). "Both female Cish genotypes exhibited similar elevations of specific cytokines, including those associated with anemia, such as TNF-α and IL-6, with only IL-18 levels higher in Cish+/+ mice following infection." (PMID 38029163, 2023). "For example, allele variants and promoter polymorphisms controlling the expression of the inflammatory cytokine tumor necrosis factor-α (TNF-α) have been associated with the propensity to develop cerebral malaria and anemia." (PMID 36146602, 2022). "Though it was not fully understood, the pathogenic processes of anemia are considered to be mediated through the actions of tumor necrosis factor (TNF)-α and interleukins (IL)-1 and -6, and interferon." (PMID 36115999, 2022). "Tumor cells produce pro-inflammatory cytokines (e.g., TNF-α, IL-1, IL-6) that cause anemia, reduce erythrocyte lifespan, and alter energy metabolism by altering iron homeostasis, inhibiting erythropoiesis and blocking EPO synthesis, and affecting EPO activity." (PMID 36567722, 2022). "TNF-α has previously been reported to be associated with the onset of anemia owing to its ability to decrease the survival of erythrocytes and affect the medullary bioavailability of iron." (PMID 35371021, 2022). "Chronic inflammation has also been associated with aging, characterized by anemia, immunosenescense, and thrombocytosis, as well as overproduction of inflammatory cytokines IL-1, TNFα, and IL-6." (PMID 34502021, 2021). "In chronic inflammatory diseases, proinflammatory cytokines such as TNF-α are present in high amounts in the circulation and are associated with anemia in most cases." (PMID 34367277, 2021). "We measured plasma levels of inflammatory and anti-inflammatory cytokines that have been previously implicated in the pathogenesis of anemia (TNF-α and its receptors (soluble TNF-RI and TNF-RII), IFN-γ, IL-6, and IL-10) in cord blood." (PMID 33995348, 2021). "It is previously shown that TNF-α is associated with weight reduction, anemia, and poor nutritional status in patients with cancer." (PMID 34395492, 2021).
anemia (continued). "Elevated levels of the pro-inflammatory cytokine tumor necrosis factor-α (TNFα) inhibit erythropoiesis and cause anemia in patients with cancer and chronic inflammatory diseases." (PMID 30546074, 2019). "Benefits include: reduced risk of surgery in those with CD, reduction in inflammatory markers, reduction in the development of anemia, improved response to anti-TNF alpha treatment, and a reduction in the risk of colo-rectal cancer." (PMID 31067701, 2019). "Several studies have associated pathology—mostly anemia and cachexia—during African trypanosome infection with the over-activation of macrophages and the resulting release of harmful molecules such as TNF-α and nitric oxide." (PMID 31824512, 2019). "Inhibition of TNFα in a zebrafish model of RPS19-deficiency was able to rescue the observed anemia, suggesting TNFα expression has a significant role in the observed phenotype." (PMID 31163577, 2019). "Increased levels of TNF, IL-6 and IL-8 as well as decreased IL-10:TNF or TGF-β1:TNF ratios are associated with anemia." (PMID 30930847, 2019). "Mechanistically, cancer-induced anemia is caused by the secretion of inflammatory factors, such as tumor necrosis factor (TNF)-α and interleukin-6 (IL-6)." (PMID 30641920, 2019). "Cytokines like TNF-α blunts erythropoietin effect and IL-1, IL-6 and interferon-γ interfere with iron metabolism causing anemia." (PMID 31387568, 2019). "By contrast, in the T. congolense model, TNF-α−/− mice exhibited similar acute anemia (and chronic) levels as control WT mice, suggesting that in this model the underlying mechanisms of anemia development are different." (PMID 29497418, 2018). "Contrary to these findings, severe anaemia in falciparum malaria has been associated with high concentrations of TNF-α and low concentrations of IL-10, with the ratio between them being the clearest indicator of disease severity." (PMID 26953797, 2016). "In humans, TNF-α is associated with adverse pregnancy outcomes such as pre-term delivery, maternal anemia and low birth weight; in murine studies, TNF-α has been associated with fetal loss." (PMID 27467392, 2016). "In humans, low birth weights are associated with severe anemia and increased TNF-α as a result of malaria infection in pregnancy." (PMID 27467392, 2016). "Systemic inflammation is a well-known cause of anemia, mediated by inflammatory cytokines such as tumor necrosis factor alpha (TNF-α), interleukin-1 (IL-1), interleukin-6 (IL-6), and interferon-γ (IFN-γ)." (PMID 26024473, 2015). "Significantly increased IL-1β transcript levels and increased secretion of TNF have been associated with placental malaria and (for TNF) with a heightened risk of severe anaemia and LBW." (PMID 24465935, 2014). "Administration of proinflammatory cytokines (IL-1 and TNF-α) in mice identifies cases of anemia associated with hyposideremia." (PMID 23091709, 2012). "The general mechanisms by which these infections lead to anaemia include blood loss, sequestration of red blood cells by the spleen, haemolysis by antibodies, and anaemia of inflammation (via TNF-alpha and IL-6 production)." (PMID 21687688, 2011). "Targeting specific inflammatory cytokines, such as IL-6 or TNF-alpha, may improve both RA symptoms and associated anemia." (PMID 39588439, 2024). "In addition, TNF‐α blocks iron recycling from macrophages, restricting iron to storage sites and initiating the development of functional iron deficiency anemia." (PMID 39240033, 2024). "The other hypothesis for anemia secondary to infection is linked to effects of various cytokine mediators of inflammation, such as tumor necrosis factor (TNF), interleukin (IL-1 and IL-6), and the interferons (IFNs)-IFNγ." (PMID 38042804, 2023).